CD63 (CD63 molecule)
Diseases named in the same sentence as CD63 in open-access papers (continued):
Sharing a sentence is not in itself a finding about the gene and the disease.
breast carcinoma (continued). "In the present study, single‐cell RNA sequencing reveals a new subset of cancer‐associated fibroblast (CD63+ CAF) in the tumor microenvironment, which downregulates ERα and PTEN expression in breast cancer cells through exosomal miR‐22 and thus induces tamoxifen resistance." (PMID 33173749, 2020). "Notably, we found that specifically inhibiting the function of CD63+ CAFs successfully enhanced the sensitivity of breast cancer to tamoxifen in an in vivo tumor model." (PMID 33173749, 2020). "Future comprehensive intervention measures that target every aspect of CD63+ CAF activity from CD63+ CAFs to exosomal miR‐22 hold promising therapeutic potential to enhance tamoxifen sensitivity and further improve the outcomes of ERα‐positive breast cancer patients." (PMID 33173749, 2020). "In addition, this nanosensing technique is able to quantify exosomes with different surface biomarker expressions and has revealed that exosomes secreted from MCF-7 breast cancer cells have a higher CD24 expression compared to CD63 and CD81." (PMID 36133621, 2019). "Antibodies against CD9 and CD63, which are enriched on EVs, were administrated to human breast cancer xenograft mouse models, and circulating administrated EVs tagged by anti-CD9 and -CD63 were internalized by macrophages through phagocytosis, resulting in the inhibition of cancer progression." (PMID 29534557, 2018). "Although the molecular mechanism underlying the cell invasiveness related to RPN2 remains unknown, our recent study reported that glycosylated CD63 by RPN2 plays an important role in breast cancer cell invasiveness by regulating MDR1 localization." (PMID 25595901, 2015). "CD63 silencing reduced the chemoresistance and invasion ability of malignant breast cancer cells." (PMID 24884960, 2014). "Furthermore, we demonstrated that CD63 and MDR1 co-localization was associated with LN metastasis in clinical samples, which suggested that co-localization of CD63 and MDR1 is likely to be a cause for treatment resistance in breast cancer patients." (PMID 24884960, 2014). "Thus, studies have implicated the TIMP-1/CD63/integrin complex in the regulation of FAK/PI3k/Akt and downstream pro-survival signaling in breast cancer." (PMID 22957045, 2012). "Using this MoS2–MWCNT based fluorometric nanosensor to analyze exosomes derived from MCF-7 breast cancer cells, we found that CD63 expression could be measured based on the retrieved fluorescence of the fluorophore with a good linear response range of 0–15% v/v." (PMID 36133621, 2019). "We characterizethe EV secretion of two breast cancer cell lines: triple-negativeMDA-MB-231 cells and HER2-positive SkBr3 cells secrete EVs that carrydistinguishable levels of tetraspanins (CD9, CD63, and CD81) and HSPs(−90 and −70)." (PMID 41489814, 2026). "HPA labelling in conjunction with ExoView analysis confirmed the co-localisation of CD63, CD81, and CD9 in both MCF-7 cell-derived sEVs and plasma-enriched sEVs derived from stage IV breast cancer patients." (PMID 40411659, 2025). "Conversely, in plasma-enriched sEVs from stage IV breast cancer patients, HPA binding was most abundant on CD81-captured sEVs, followed by CD9, with the least binding on CD63-captured sEVs." (PMID 40411659, 2025). "We isolated TDEs from E0771 breast cancer cell supernatant and validated their identity by CD9, CD63, and GAPDH expression, nanoparticle tracking analysis (NTA), and transmission electron microscopy (TEM)." (PMID 40695812, 2025). "In contrast, for sEVs from MCF-7 cells derived from breast cancer metastasis, there was a 1.5-fold higher abundance of CD81 than CD63 (p < 0.001)." (PMID 40411659, 2025). "For example, the CD63 protein marker showed differences in MCF7 and MDA-MB-231 cells, although both of them are breast cancer cell lines." (PMID 37242792, 2023).
breast carcinoma (continued). "This is consistent with previous studies reporting an increase in CD63‐pHlourin events upon histamine stimulation of HeLa and HUVEC cells, and ionomycin stimulation of the breast cancer cell line MDA‐MB‐231." (PMID 38938673, 2023). "To determine the applicability of our findings to a broader context, we analyzed a breast cancer patient cohort for expression of CD74, CD63, and TIMP‐1 by immunohistochemistry (IHC)." (PMID 37081824, 2023). "In breast cancer, non-invasive detection through urinary biomarkers, such as MMP9, NGAL, CD63, ECM1, MAST4, and Filaggrin, offers insights into disease progression." (PMID 38250812, 2023). "CD63+ CAFs have been reported to secrete miR-22-rich exosomes, which act through its targets, ERalpha and PTEN, to confer tamoxifen resistance in breast cancer cells." (PMID 35326670, 2022). "In summary, the surface protein profile of EVs from breast cancer patients suggested that EVs with the typical EV markers CD9, CD63 and CD81 were of cancer cell origin, as well as released by antigen-presenting cells and platelets." (PMID 35012489, 2022). "The expression of characteristic markers for exosomes and EVs varied, but all EV lysates from breast cancer lines were positive for CD9 and CD81, whilst the presence of CD63 was more variable." (PMID 35318648, 2022). "It does seem to hold the same properties, though, in breast cancer in regard to cell migration and proliferation as CD9 and CD63, and suppression of this surface protein is reported to reduce cancer invasion and metastasis." (PMID 36555738, 2022). "In turn, STAT3 increases TIMP-1 secretion by breast cancer cells, leading to a TIMP-1/CD63/integrin β1/STAT3 positive feedback loop, which can be further fueled by IL-6." (PMID 36291767, 2022). "Both the breast cancer and melanoma studies have focused on the impact of CD81+CD63+EVs in inhibiting lung metastasis and it remains to be seen if this impact of CD81+CD63+EVs is restricted to the lung or if it also impacts metastasis to the other organs." (PMID 34503207, 2021). "In the same year, Etayash and his research team reported a cantilever array for simultaneously detecting overexpressed membrane proteins CD24, CD63, and EGFR in exosomes derived from breast cancer." (PMID 34940275, 2021). "BCSCs express TIMP-1 that synthesizes the ligand CD63, further regulates the survival and induces EMT (epithelial-mesenchymal transition) of breast cancer cells." (PMID 34611125, 2021). "For BCSC-immune cell cross-talk, LGALS1-PTPRC, NECTIN2-CD96, and NECTIN2/4-TIGIT are found to hamper immunity against breast cancer; by expressing TIMP-1, BCSC promotes epithelial-mesenchymal transition (EMT) by interacting with CD63 in epithelial cells." (PMID 34611125, 2021). "The common EV markers CD9, CD63 (category 1), and ALIX (category 2) were confirmed from the EVs from breast cancer cells exposed to each temperature, supporting the presence of EVs." (PMID 33408817, 2020). "Collectively, these results indicate that miR‐22, which is enriched in CD63+ CAF‐derived exosomes, mediates tamoxifen resistance in breast cancer." (PMID 33173749, 2020). "By analyzing the publicly available scRNA‐seq data of human primary breast cancer, we confirmed that TIMP1 expression in CAFs with high CD63 expression was significantly higher than in CAFs with low CD63 expression." (PMID 33173749, 2020). "The evaluation of the exosome preparations by confocal microscopy demonstrated that breast cancer cells (MCF-7), as well as activated T-lymphocytes, presented an increased number of exosomes (based on CD63 labeling)." (PMID 30922347, 2019). "TIMP‐1 interacts with a complex of the tetraspanin cluster of differentiation 63 (CD63) and integrin β1 at the cell membrane, and CD63 down‐regulation decreases TIMP‐1 presence at the cell surface and reduces cell survival in breast cancer cells." (PMID 31545548, 2019).
breast carcinoma (continued). "To directly image breast cancer–derived exosomes, we established a MDA-MB-231/CD63-RFP cell line that stably expresses CD63-RFP protein." (PMID 29484119, 2018). "In epithelial breast cancer cells, TIMP1 induced TWIST1 expression, leading to E-cadherin downregulation and epithelial mesenchymal transition in a CD63-dependent manner." (PMID 28430130, 2017). "In our study, the breast cancer tissue samples tested had increased T cell and macrophage immune cell marker (CD4, CD25, CD63, CD163) expression compared to benign tissue." (PMID 26964534, 2016). "For example, exosomes derived from metastatic MDA-MB-231 breast cancer cells were determined to be 40–120 nm in size by SEM and contained the typical exosomal marker CD63." (PMID 26601108, 2015). "Our current results indicate that CD63 glycosylation by RPN2 is important for the localization of CD63 and MDR1 in human breast cancer cells." (PMID 24884960, 2014). "To determine the relationship between CD63 and MDR1 in clinical samples, we performed immunofluorescent staining of CD63 and MDR1 in a 69 breast cancer tissue microarray." (PMID 24884960, 2014). "By employing two distinct aptamers targeting the characteristic proteins of exosomes (CD63, EpCAM), the synergistic effect of the dual aptamers enabled the precise capture of breast cancer exosomes and minimized the interference from nonspecific binding." (PMID 41041069, 2025). "To identify the ArfGAPs that regulate CD63 transport to ILVs, we used the human mammary carcinoma cell line MCF7, as we could see clear localization of CD63 inside enlarged endosomes by overexpression of Rab5Q79L." (PMID 38682696, 2024). "For example, glycosylation of CD63 (TSPAN30) in breast cancer cells by RPN2, part of the N-oligosaccharyle transferase complex, could stabilize CD63 on the cell membrane." (PMID 36941633, 2023). "Thus, the higher colocalization of CD63 and ITGAV suggests a higher probability of ITGAV export into EVs in advanced breast cancer." (PMID 35923105, 2022). "In xenograft breast cancer model mice, circulating EVs derived from tumor cells were captured by anti-human CD9 and anti-human CD63 antibodies stimulating EV removal by macrophages internalization, associated with a decreased metastasis formation into the lungs, lymph nodes, and thoracic cavity." (PMID 33869035, 2021). "Our screen assessed several known CD markers and identified several novel (i.e. CD63, CD98 and CD164) and less characterised (i.e. CD46, CD107a and CD321) breast epithelial markers, of which are overexpressed in at least 5% of breast cancer samples in the COSMIC database." (PMID 34120626, 2021). "To identify signatures of CD81+CD63+EVs, we applied unsupervised hierarchal clustering to stratify non-metastatic breast cancer patients into two groups with 182 and 268 patients each." (PMID 34503207, 2021). "Furthermore, it is discovered that CD63+ CAFs secrete exosomes rich in miR‐22, which can bind its targets, ERα and PTEN, to confer tamoxifen resistance on breast cancer cells." (PMID 33173749, 2020). "Both breast cancer cell lines induced higher CD62P and CD63 IPA in WB than the non-tumorigenic MCF10A cell line (p > 0.05); with MCF7 cells inducing significantly higher CD62P, and T47D cells induced significantly more CD63 IPA, compared to WB." (PMID 33159119, 2020). "Then, we treated ERα‐positive BCs or breast cancer organoids with CAF‐derived exosomes and observed that CD63+ CAF‐derived exosomes could induce ERα downregulation." (PMID 33173749, 2020). "Furthermore, CD63-1 was found to be efficient in binding CD63 positive cells, including breast cancer MDA-MB-231 cells and CD63-overexpressed HEK293T cells, with a medium binding affinity (Kd ~ 100 nM) as assessed by flow cytometry." (PMID 33261145, 2020).
breast carcinoma (continued). "After optimization of the exosome isolation from MDA-231 breast cancer cells in 2D cultures we verified the successful exosome harvesting through TEM and immunoblot protein analysis of well-established exosome markers CD63 and CD81." (PMID 29137633, 2017). "From these cell lines, the transfer of CD63-GFP exosomes to nonfluorescent autologous breast cancer cells was visualized in vitro and in xenograft models." (PMID 26601108, 2015). "Others have reported CD63, ALG-2-interacting protein X (Alix), which is involved in exosome biogenesis and endosomal sorting, and TSG101, or a combination of these proteins, from MDA-MB-231, MCF-7, T47D:A18, and Hs-578T breast cancer-derived exosomes." (PMID 26601108, 2015). "An association between cancer malignancy and the co-localization of MDR1 and CD63 in breast cancer clinical samples has not been reported." (PMID 24884960, 2014). "Exposure of three different breast cancer cell lines to moderate (1% O2) and severe (0.1% O2) hypoxia resulted in significant increases in the number of exosomes present in the conditioned media as determined by NTA and CD63 immunoblotting." (PMID 22998595, 2012). "Additionally, breast cancer MDA-MB-231 cells showed increased EVs (approximately 1.5-fold) after paclitaxel treatment, in which survivin-carrying EVs were upregulated, although exosomal CD63-carrying EVs were downregulated." (PMID 37823055, 2023). "In addition to EGR1, CD63 and BIRC3 were also found to be associated with breast cancer, while USF2′s role in breast cancer has not been clearly investigated." (PMID 34252628, 2021). "CD63, a member of transmembrane-4-superfamily of tetraspanin proteins and a highly N-glycosylated type III lysosomal membrane protein, is known to regulate malignancy of various types of cancers such as melanoma and breast cancer and serves as a potential marker for cancer detection." (PMID 33261145, 2020). "Furthermore, we determined that CD63+ CAFs could promote tamoxifen resistance through exosomal miR‐22, which downregulated ERα and PTEN expression in breast cancer cells." (PMID 33173749, 2020). "In summary, the study reveals a novel subset of CD63+ CAFs that induces tamoxifen resistance in breast cancer via exosomal miR‐22, suggesting that CD63+ CAFs may be a novel therapeutic target to enhance tamoxifen sensitivity." (PMID 33173749, 2020). "Moreover, deleting CD81 in endothelial-producing exosome cells but not tetraspanins CD63 or CD82 reduced breast cancer motility and metastasis." (PMID 29946318, 2018). "To assess if other human mammary epithelial cells release exosomes, we quantified the abundance of CD81 and CD63, an endosomal marker protein, in P70 preparations of breast cancer cell lines MDA-MB-231, BT-20, and the nontumorigenic mammary epithelial cell line MCF 10A." (PMID 20976003, 2010). "Herein, the authors explored the sensing of general exosome biomarkers (CD9, CD63, and CD81), and cancer-related biomarkers (CD24, CD44, CD54, CD326, and CD340) which could be identified on exosomal surfaces derived from the three distinct breast cancer cell lines (MCF-7, MDA-MB-231, and SK-BR-3)." (PMID 38425422, 2024). "Our study indicates that CD63+ CAFs in the TME constitute a survival niche for BCs that can protect them from tamoxifen during cancer progression, which suggests that CD63+ CAFs may serve as a novel therapeutic target to enhance tamoxifen sensitivity in breast cancer." (PMID 33173749, 2020). "Western blot analysis showed that the Luc2 mouse mammary carcinoma cells expressed CD9 and CD81 but not CD63." (PMID 39273689, 2024). "CD63, ITGB1, and ITGAV were abundant on the cell surface of breast cancer cells while CD11b was lacking." (PMID 35923105, 2022). "Collectively, studies with these non-metastatic breast cancer cells demonstrated that despite enhanced tumor-forming potential in vitro, cell lines secreting CD81+CD63+EVs were rejected in vivo, presumably due to the host immune system." (PMID 34503207, 2021).
breast carcinoma (continued). "The downregulation of tetraspanin CD63- or CD9-positive EVs by paclitaxel was also observed in MDA-MB-231 and HCC1937 breast cancer cells, implying that non-exosomal EV subtypes could be generated by paclitaxel." (PMID 37823055, 2023). "Moreover, recent studies in breast cancer cells have shown the release of hypothetical “non-classical” exosomes generated by amphisomes (produced by fusion of multivesicular bodies -MVB- and autophagosomes)), lacking classical exosome markers (CD63, CD81, and CD9)." (PMID 38268920, 2023).